MUTYH (mutY DNA glycosylase)
Diseases named in the same sentence as MUTYH in open-access papers (continued):
Sharing a sentence is not in itself a finding about the gene and the disease.
Lynch syndrome (continued). "A large proportion of non-FAP non-Lynch syndrome patients with multiple colorectal adenomas have germline mutations on the MUTYH gene." (PMID 19822006, 2009). "Initially, she was suspected to have FAP or Lynch syndrome, but genetic testing revealed no pathogenic variants in APC, MUTYH, or mismatch repair genes." (PMID 40741356, 2025). "Because there is an overlap between the clinical and molecular characteristics of MUTYH-associated tumor syndrome and Lynch syndrome, underlying constitutional variants in MMR genes must be ruled out before considering MUTYH deficiency as potential diagnosis." (PMID 40225933, 2024). "For patients without Lynch syndrome, APC was identified as the gene associated with the most mutations (n = 14) and was followed by BRCA1 (n = 8), RAD50 (n = 7), MUTYH (n = 5), ATM (n = 5), and BRCA2 (n = 4)." (PMID 35014770, 2022). "Of 20 patientsinitially referred for Lynch syndrome, 3 had PV/LPVs on retesting, and noneultimately had this condition (CHEK2, MITF, MUTYH heterozygote,n = 1 each)." (PMID 34545504, 2022). "In addition, we identified 2 patients who had a deleterious germline mutation in Lynch syndrome genes (MLH1 and MLH2), and another 8 patients harbored germline mutations of 6 non-Lynch syndrome genes (MUTYH, GALNT12, POLE, MPL, ATM, and ERCC4) which may be associated with endometrial cancer." (PMID 30886832, 2019).
adenoma (29 papers, 2008 to 2026). A neoplasm arising from the epithelium. "As it is well known, adenomas and tumors coming from MUTYH biallelic carriers show a deficiency in the 8-oxo-hidroxyguanine repair system, leading to an increase in the G > T mutation rate, frequently in APC and KRAS15." (PMID 31285513, 2019). "Another patient (308#1260), with recurrent adenomas at endoscopic follow-up, was a compound heterozygote for the c.1145GA (p.Gly382Asp) and the c.1395_1397delGGA (p.Glu466del) variants of MUTYH that were previously reported as pathogenic." (PMID 24278394, 2013). "The penetrance for colon polyps is close to 100% and bi-allelic MUTYH mutation carriers generally develop 10-100 adenomatous polyps/adenomas of the colon and rectum." (PMID 19822006, 2009). "In the applied studies, the incidences of biallelic MUTYH mutations in the groups of patients having 15-100 adenomas, were found to be between 16-47% (N=835)." (PMID 19506731, 2008). "We revealed that MAP adenomas have approximately two to four times the number of coding region somatic mutations when compared to FAP adenomas, and that these mutations are overwhelmingly G:C → T:A mutations, in keeping with the expected signature associated with MUTYH loss." (PMID 26414517, 2016). "Two early papers suggested a significant association with adenomas and cancer, and subsequent analysis of the patients in the early cohorts showed that most cases could be accounted for by germline MUTYH mutations." (PMID 24416237, 2014). "In addition, the altered function of enzymes involved in the repair of oxidative DNA damage, e.g., 8-oxoguanine DNA N-glycosylase 1 (hOGG1) and mutY DNA glycosylase (MUTYH), results in the accumulation of DNA mutations and contributes to the adenoma-adenocarcinoma transition." (PMID 39334768, 2024). "We showed that in MUTYH-associated polyposis, a hereditary colorectal cancer syndrome marked by impaired BER, adenomas exhibit a pronounced hypomethylation." (PMID 34372923, 2021). "In this study we explored the somatic mutational landscape of early‐stage premalignant adenomas from patients with germline mutations in APC and MUTYH as a first step towards defining the catalogue of mutated genes." (PMID 26414517, 2016). "Genetic testing for MUTYH and other polyposis‐associated genes is typically recommended for individuals with more than 10 adenomas; however, there are no clear guidelines for MUTYH testing that consider the variable polyp burden in MAP." (PMID 41347765, 2026). "Patients under 60 years with 10 or more adenomas, and those over 60 with 20 or more adenomas or 10 or more adenomas with a family history of adenomas or CRC but without pathogenic variants in APC or MUTYH are categorized as having “multiple colorectal adenomas”." (PMID 39057027, 2024). "Of the 31 patients with early-onset colon cancer and advanced adenoma, 17 had germline testing, and 3 patients had PGVs (BRCA1, monoallelic EPCAM [OMIM 185535], and monoallelic MUTYH [OMIM 604933])." (PMID 37462969, 2023). "Of 31 patients with early-onset colon cancer found to have advanced adenomas, 17 had germline testing data, and 3 patients had PGVs (1 each in BRCA1, EPCAM [monoallelic], and MUTYH [monoallelic] genes)." (PMID 37462969, 2023). "When compared to Polyposis patients without mutations in neither the MUTYH nor the APC gene, MAP patients seemed to develop the lowest number of adenomas, although no statistically significant results have been found." (PMID 19506731, 2008). "A characterization of the somatic mutational profile performed with WES of colorectal adenomas from FAP and MAP patients showed that adenomas from MAP patients had a higher rate of missense and nonsense mutations compared with FAP adenomas, due to genetic defects in the MUTYH gene." (PMID 33923068, 2021).
colon cancer (24 papers, 2008 to 2026). "While MUTYH mutations are typically associated with colon cancer, increasing evidence suggests their pathogenic potential in BC." (PMID 38028594, 2023). "Outside of colon cancer, somatic MUTYH mutations have also been described in breast cancers and in 0.24% of ovarian cancer samples." (PMID 33419231, 2021). "While somatic and biallelic MUTYH mutations are associated with an increased risk of ovarian cancer, the majority of mechanistic studies have been performed in colon cancer model systems." (PMID 33419231, 2021). "In both studies, index cases were identified in patients with colon cancer who were enrolled in a cancer registry study and the association of MUTYH mutations with non-colonic tumors in affected family members was assessed." (PMID 33419231, 2021). "Individuals with biallelic pathogenic/likely pathogenic variants in MUTYH are associated with a lifetime risk of colon cancer of up to 80%." (PMID 32090079, 2020). "The role of MUTYH mutations in extra-colonic cancers has previously been reviewed and there are indications that this gene is associated with a broader spectrum of disease." (PMID 19338676, 2009). "Since the MMR genes, hMSH2 and hMSH6 are associated with HNPCC and evidence suggests that they directly interact with MUTYH, it is possible that MUTYH mutations are related to HNPCC extra-colonic cancers, specifically endometrial cancer." (PMID 19338676, 2009). "In addition, in families with MUTYH gene mutation exist a risk for a predisposition to juvenile colon cancer as others reported having." (PMID 31207142, 2019). "Notably, prior studies have indicated that altered BER capacity can lead to a higher incidence of cancer, such as the elevated colon cancer risk for MUTYH mutant carriers." (PMID 30167090, 2018). "Whether monoallelic pathogenic variants in MUTYH also increase cancer risk is unclear, although there is some evidence suggesting a slight increase, especially when there is a family history of colon cancer." (PMID 27014339, 2016). "The association between MUTYH heterozygosity and SBS18 was also present in many extra-colonic cancers, including other gastrointestinal tumours, but the raised SBS18 did not detectably increase the risk of these cancers." (PMID 42092060, 2026). "On the other hand, in the normal and tumoral colon tissue of a patient affected by colon cancer (not carrying any MUTYH variants), expression is similar and is localized in both the nuclei and the cytoplasm." (PMID 38790183, 2024). "For the cancer susceptibility genes identified in the cohort that are not involved in LS, we found several genes implicated in the hereditary colorectal cancer landscape: APC, MUTYH, POLE, POLD1, and BLM, as well as genes resulting in an increased risk of colon cancer as CHEK2." (PMID 36232851, 2022). "Results from previous studies point towards a role of MUTYH mutations in HNPCC and suggest that they may be involved in a larger spectrum of disease involving extra-colonic cancers." (PMID 19338676, 2009). "In addition, another female patient was detected to harbor only the c.650G>A in the MUTYH gene while being negative for the second variant (c.884C>T) found in the proband (a son affected by colon cancer)." (PMID 38136276, 2023).
ovarian carcinoma (24 papers, 2014 to 2025). A malignant neoplasm originating from the surface ovarian epithelium. "Concurrent pathogenic germline mutations in MLH1, PMS2, and MUTYH were found in three patients (two in uterine cancer and one in ovarian cancer)." (PMID 37310942, 2023). "PPM1D variants have been associated with predisposition to breast and ovarian cancers along with MUTYH and CHEK2." (PMID 36555431, 2022). "The purpose of this article is to describe the role of MUTYH mutations in the pathogenesis of cancer and describe its emerging use in early detection, treatment decisions, and possible targeted therapies for ovarian cancer." (PMID 33419231, 2021). "Understanding the function of MUTYH and its associated partners is critical for determining screening, risk reduction, and therapeutic approaches for MUTYH-driven ovarian cancers." (PMID 33419231, 2021). "Consistent with the estimated prevalence of carrying a heterozygous MUTYH germline mutation, monoallelic germline MUTYH mutations have been identified in 1.9% of ovarian cancer patients." (PMID 33419231, 2021). "Another potential targeted therapy for ovarian cancers resulting from MUTYH mutations includes PARP inhibitors." (PMID 33419231, 2021). "As MUTYH is intimately associated with targetable molecular partners, therapeutic options for MUTYH driven ovarian cancers include programed-death 1/programed-death ligand-1 inhibitors and poly-adenosine diphosphate ribose polymerase inhibitors." (PMID 33419231, 2021). "The risk for the development of ovarian cancer in patients with biallelic MUTYH germline mutations has been evaluated in two studies." (PMID 33419231, 2021). "Indeed, monoallelic germline MUTYH variants have been recurrently detected in patients affected by breast/ovarian cancer, as well as in patients with prostate cancer, endometrial and gastrointestinal cancers, including Lynch syndrome." (PMID 38790183, 2024). "As part of our routine diagnostic work-up, we have detected MUTYH germline heterozygous variants in a number of patients affected by breast/ovarian cancer or endometrial cancer who underwent a targeted gene panel analysis, as requested by the clinical geneticist." (PMID 38790183, 2024). "Further study is necessary to determine whether individuals with ovarian cancer and biallelic germline pathologic variants in MUTYH demonstrate this potential resistance to alkylating agents." (PMID 35685436, 2022). "MUTYH mutations may confer the risk of ovarian cancer by the failure of its well-known base excision repair mechanism or by failure to induce cell death." (PMID 33419231, 2021). "This similar treatment phenomenon suggests a similar mechanism could be involved in MUTYH-mutated ovarian cancers." (PMID 33419231, 2021). "Although approximately 18% of all ovarian cancers are the result of an inherited predisposition, it is unknown how many of these ovarian cancers are directly attributable to biallelic MUTYH mutations." (PMID 33419231, 2021). "Biallelic MUTYH mutation is associated with an increased risk of ovarian cancer." (PMID 33419231, 2021). "As MUTYH mutations may drive some ovarian cancers, it is critical to anticipate how these tumors may respond to these therapies." (PMID 33419231, 2021). "Due to the multitude of DNA damage repair mechanisms controlled by MUTYH, it is reasonable to suspect that multiple ovarian cancer histologies may be associated with this alteration." (PMID 33419231, 2021). "This chemoprevention strategy may reduce the risk of ovarian cancer in populations with varying levels of pre-existing risk, including those with biallelic MUTYH germline mutations; however, prospective studies are needed." (PMID 33419231, 2021).
ovarian carcinoma (continued). "Although COSMIC has identified somatic MUTYH mutations in 0.24% (3/1229) of curated ovarian cancers, many oncology practices only test ovarian cancer patients with next-generation sequencing for somatic BRCA1/2 mutations or mismatch repair deficiency, suggesting this rate may be an underestimate." (PMID 33419231, 2021). "In this study, the c.849 + 3A > C (rs587780751) in the MUTYH gene was found in a patient with early onset ovarian cancer and with other cases of breast, prostate and lung cancers (P15)." (PMID 36035419, 2022). "Lastly, there are genes related to other familiar cancer syndromes linked to an increased risk of ovarian cancer, such as PTEN (PTEN tumor hamartoma syndrome), STK11 (Peutz-Jeghers syndrome) and MUTYH (MUTYH-associated polyposis)." (PMID 32512900, 2020). "MUTYH may contribute to the development of sporadic ovarian cancer via the well-described “incessant ovulation” hypothesis, “gonadotropin hypothesis”, or serous tubal intraepithelial carcinoma (STIC) hypothesis." (PMID 33419231, 2021). "The pathogenic variants in BC-related genes (2 in ATM and 1 in BRCA2) were found in 3 women with BC or ovarian cancer, while the MSH6 and the heterozygous MUTYH p.Gly393Asp pathogenic variant was found in a woman with endometrial cancer at 57 years and BC diagnosis at 56 years, respectively." (PMID 29371908, 2018). "Similarly to ovarian cancer, esophageal cancer also loses its initial sensitivity to platinum and develops resistance, suggesting that a similar mechanism to MUTYH could be at work in ovarian cancer." (PMID 37240218, 2023).